RAB27B (RAB27B, member RAS oncogene family)
Description:
The small GTPases Rab are key regulators of intracellular membrane trafficking, from the formation of transport vesicles to their fusion with membranes. Rabs cycle between an inactive GDP-bound form and an active GTP-bound form that is able to recruit to membranes different sets of downstream effectors directly responsible for vesicle formation, movement, tethering and fusion. RAB27B regulates homeostasis of late endocytic pathway, including endosomal positioning, maturation and secretion. Plays a role in NTRK2/TRKB axonal anterograde transport by facilitating the association of NTRK2/TRKB with KLC1. May be involved in targeting uroplakins to urothelial apical membranes (By similarity).
Synonyms: C25KG
Tractability: Small molecule: a structure with a bound ligand is known. Antibody: its Gene Ontology location is reachable by antibodies, with high confidence; the Human Protein Atlas places it where antibodies can reach. PROTAC: ubiquitination databases record sites on it; its protein half-life has been measured.
Gene: Protein-coding gene on chromosome 18 (54,717,857 to 54,895,516, forward strand). Ensembl gene ENSG00000041353.
Subcellular location: Membrane; Late endosome
Subcellular location (Human Protein Atlas): Golgi apparatus; Plasma membrane; Cytosol
Pathways (Reactome):
Hemostasis: Platelet degranulation
Metabolism of proteins: RAB geranylgeranylation
Vesicle-mediated transport: RAB GEFs exchange GTP for GDP on RABs
Gene Ontology:
Molecular function: GDP binding; GTP binding; myosin V binding; protein binding; protein domain specific binding; G protein activity; GTPase activity
Biological process: multivesicular body sorting pathway; positive regulation of exocytosis; anterograde axonal protein transport; exocytosis; regulation of exocytosis; synaptic vesicle endocytosis
Cellular component: extracellular exosome; Golgi apparatus; Golgi stack; late endosome; melanosome; multivesicular body membrane; trans-Golgi network transport vesicle; apical plasma membrane; exocytic vesicle; plasma membrane; platelet dense granule membrane; secretory granule; axon cytoplasm; membrane; synaptic vesicle membrane; zymogen granule membrane
Genetic constraint (gnomAD): Loss-of-function variants: 11 observed, 18.91 expected, observed/expected ratio (o/e) 0.58, 90% interval 0.37 to 0.96. The upper end of that interval is the gene's LOEUF score, 0.96, which puts it in group 4 of 6, group 1 being the genes least tolerant of losing a copy. Missense variants: 228 observed, 229.01 expected, observed/expected ratio (o/e) 1, 90% interval 0.89 to 1.11. Synonymous variants: 86 observed, 81.37 expected, observed/expected ratio (o/e) 1.06, 90% interval 0.89 to 1.26.
Homologues: Orthologues: chimpanzee RAB27B (99% identical), macaque RAB27B (99% identical), dog RAB27B (97% identical), guinea pig RAB27B (96% identical), rabbit RAB27B (96% identical), mouse Rab27b (94% identical), pig RAB27B (94% identical), rat Rab27b (94% identical), tropical clawed frog rab27b (89% identical), zebrafish rab27b (83% identical). Paralogues in human: RAB27A (72% identical), RAB3D (39% identical), RAB8A (39% identical), RAB3A (39% identical), RAB10 (39% identical), RAB3C (39% identical), RAB3B (38% identical), RAB37 (38% identical), RAB8B (38% identical), RAB13 (37% identical), RAB26 (37% identical), RAB1B (36% identical), and 56 more.
Diseases named in the same sentence as RAB27B in open-access papers:
RAB27B is named in the same sentence as 70 diseases in open-access papers, as found by Europe PMC text mining. Sharing a sentence is not in itself a finding about the gene and the disease. The quoted sentences say what the papers report.
breast carcinoma (34 papers, 2010 to 2025). "Mechanistically, the RAB27B expression was linked to lymph node metastasis and differentiation in breast cancer." (PMID 35164665, 2022). "V-ATPase was found to be required for Rab27B-dependent invasive growth and metastasis in breast cancer suggesting that V-ATPase and the Rab GTPase implicated in exosome biogenesis were functionally connected." (PMID 31339911, 2019). "High expression of Rab27B is associated with reduced survival times in patients with breast cancer and bladder cancer." (PMID 30081925, 2018). "Rab27B regulates invasive growth and metastasis in estrogen-receptor-positive breast cancer cell lines, and increased expression is associated with poor prognosis." (PMID 26196085, 2015). "A growing number of Rab proteins such as rab5, rab11, rab21, rab25, and rab27B have been shown to be associated with tumor growth/behavior and prognosis of breast cancer patients." (PMID 22920728, 2012). "In human breast cancer specimens, the presence of Rab27B protein proved to be associated with a low degree of differentiation and the presence of lymph node metastasis in ER-positive breast cancer." (PMID 21304180, 2010). "TGF‐β and the loss of RAB27B promote higher quantity of protein loading with EVs, especially exosomes, which inhibit CD8+ T cell‐mediated killing of breast cancer cells." (PMID 39723610, 2024). "Recent investigations mainly focused on the role of RAB27B in cancers, such as breast cancer, bladder cancer, and glioma." (PMID 35164665, 2022). "Collectively, this study provides experimental evidence for PRKCE/AURKB/RAB27B axis in regulating the resistance to paclitaxel (PTX) in breast cancer cells, offering a potential intervention target for reversing drug resistance." (PMID 35088239, 2022). "Rab27B-dependent invasive growth and metastasis of breast cancer is reliant on V-ATPase activity, with the V-ATPase V1E protein expressed in the majority of breast cancer patients with poor prognosis." (PMID 36046070, 2020). "RAB27B has been shown to regulate invasive growth in vitro and in vivo in estrogen receptor (ER)-positive breast cancer cell lines and to be involved in osteosarcoma cell migration and invasion." (PMID 32379831, 2020). "With respect to RAB27B, metabolic reprogramming mediated by RAB27B was verified to induce doxorubicin resistance in breast cancer cells, and it was found that RAB27B is involved in chemoresistance to cisplatin in pancreatic cancer." (PMID 32379831, 2020). "Elevated expression of Rab27A has been demonstrated in tumor specimens from patients with melanoma and hepatocellular carcinoma, whereas elevated expression of Rab27B has been found in tumor specimens from patients with breast cancer." (PMID 30081925, 2018). "Although there were few mechanism researches that inspected the characteristics of Rab27b, it was identified to fuel invasion growth and metastasis of breast cancer and facilitate proliferation of HCC cells by regulating the PI3K/AKT/p21 pathway." (PMID 30627227, 2018). "Recent studies have revealed that Rab27A and Rab27B control exosome secretion in various cell types, including dendritic cells, cervical cancer cells, breast cancer cells, melanoma cells, bladder cancer cells, and lung cancer cells." (PMID 30081925, 2018). "In another study of breast cancer, the heat-shock protein HSP90α was found in the exosomes isolated from Rab27B-overexpressing cells." (PMID 30081925, 2018). "High Rab27b expression also indicated poor prognosis in ovarian cancer, breast cancer, pancreatic cancer, and colorectal cancer." (PMID 30627227, 2018). "For examples, the increased Rab27B expression correlates with lymph node metastasis and is a marker for breast cancer progression." (PMID 28265202, 2017). "In breast cancer cell lines, expression of Rab27B promotes cell cycle progression, proliferation, and invasion and this activity is dependent on the geranylgeranylation of Rab27B." (PMID 28555000, 2017).
breast carcinoma (continued). "Rab27B promotes invasive growth and metastasis of estrogen receptor (ER)-positive breast cancer cells." (PMID 29088864, 2017). "In another study, heat-shock protein 90α has been identified in RAB27B-secretory vesicles as a key pro-invasive growth regulator inducing activation of matrix metalloproteinase-2 in breast cancer." (PMID 28784136, 2017). "Increased expression of RAB27B has been shown to predict a poor outcome in patients with breast cancer." (PMID 29284484, 2017). "Our obtained survival data are in line with the previous researches that describe the prognostic role of Rab27b in breast cancer and HCC." (PMID 25580113, 2014). "Rab27B has been suggested to function as an oncogene in breast cancer because it is responsible for regulating many secretory mechanisms." (PMID 25382899, 2014). "Rab27b regulates invasive tumor growth of breast cancer cells using and overexpression of the Rab27b indicates poor prognosis in breast cancer (BC) and hepatocellular carcinoma (HCC)." (PMID 25580113, 2014). "Work from our group demonstrated that Rab27B promotes invasive growth and metastasis of estrogen receptor (ER)-positive breast cancer cells." (PMID 23665896, 2013). "One approach involves the complete determination of exosome-enriched fractions and exosome-depleted conditioned media of control versus Rab27B overexpressing breast cancer cells." (PMID 23665896, 2013). "Rab27B overexpression in breast cancer cells resulted in a four-fold increase in the release of HSP90α." (PMID 23665896, 2013). "Breast cancer cells in which Rab27B was overexpressed formed cellular extensions and a spread morphology and had a significant increased ability to invade Matrigel and native type I collagen substrates." (PMID 23665896, 2013). "We investigated the biological role and expression status of Rab27B, a regulator of exosome release, in breast cancer." (PMID 26082068, 2012). "Proteomics of purified Rab27B vesicles and the secretome of Rab27B-expressing breast cancer cells were identified HSP90α as key proinvasive growth regulator." (PMID 26082068, 2012). "The sensitivity and specificity of Rab27B as a prognosis prediction marker of breast cancer patients are 88.2 and 63.5 respectively." (PMID 23217148, 2012). "The secretory small GTPase Rab27b was recently identified as an oncogene in breast cancer (BC) in vivo and in vitro studies." (PMID 23217148, 2012). "Since estrogen regulates vesicle trafficking gene expression in ER-positive breast cancer cells, it is of interest to determine Rab27A and Rab27B mRNA and protein levels in additional estrogen-dependent carcinomas such as ovarian carcinoma." (PMID 21304180, 2010). "We next examined whether TGF‐β can downregulate the expression of RAB27B in other breast cancer cell lines including BT‐549, MCF‐7, MDA‐MB‐436, SUM149, BT‐474, and cervical cancer cells HeLa." (PMID 39723610, 2024). "Taken together, we identified that TGF‐β in breast cancer cells reduces the release of EVs, but upregulates the quantity of protein loaded into EVs, particularly exosomes, by downregulating the expression of RAB27B." (PMID 39723610, 2024). "Collectively, the findings obtained in our study may provide experimental evidence for the involvement of the PRKCE/AURKB/RAB27B axis in the resistance of breast cancer cells to PTX and offer a potential intervention target for reversing tumor drug resistance." (PMID 35088239, 2022). "Finally, the participation of Rab27A and Rab27B in management of exosomes has been confirmed in: mouse melanoma, mouse breast cancer, and human squamous cell carcinoma cells for Rab27A and in HeLa cells both for Rab27A and Rab27B." (PMID 34943891, 2021). "Moreover, exosome transfer from stroma to cancer cells regulated by stromal RAB27B is involved in therapeutic resistance in breast cancer." (PMID 32379831, 2020).
breast carcinoma (continued). "Additionally, ectopic overexpression of Rab27B enhances in vitro cell invasion of breast cancer cells (MCF-7, T47D).Overexpression of Rab27B also increases in vivo muscular invasion of xenografts derived from MCF-7 breast cancer cells." (PMID 30081925, 2018). "Rab27B has been reported to promote invasion and metastasis of breast cancer cells." (PMID 29088864, 2017). "In addition, Rab27B regulates invasive tumor growth of colorectal cancer, hepatocellular carcinoma and breast cancer." (PMID 28265202, 2017). "Rab27B-upregulation in estrogen receptor (ER)-positive breast cancer cells promoted G1/S phase cell cycle transition and increased proliferation, F-actin reorganization and invasion in cell culture and invasive tumor growth and hemorrhagic ascites in a xenograft mouse model." (PMID 26082068, 2012). "Notably, in agreement with our data, a recent report includes SEL1L peptides among the proteins identified by mass spectrometry in purified Rab27b-secretory vesicles of MCF7 breast cancer cells." (PMID 21359144, 2011). "Overexpression of the Rab27B protein to comparable expression levels found in poor prognosis primary breast cancer resulted in G1 to S phase cell cycle transition, growth and invasiveness of cells in cell culture, and invasive tumor growth and hemorrhagic ascites production in nude mice." (PMID 21304180, 2010). "Thus, overexpression of Rab27B contributed to the EMT process in breast cancer progression." (PMID 30081925, 2018). "In addition, Rab27B proteins have been reported to be positively correlated with invasion and metastasis in colorectal cancer, hepatocellular carcinoma and breast cancer, and these proteins mediate exosome secretion of tumor-related miRNAs and proteins such asproteases." (PMID 26913720, 2016). "We recently discovered that the secretory small GTPase Rab27B, a regulator of vesicle exocytosis, delivers proinvasive signals for increased invasiveness, tumor size, and metastasis of various estrogen receptor (ER)-positive breast cancer cell lines, both in vitro and in vivo." (PMID 21304180, 2010). "TGF‐β‐EVs and shRAB27B‐EVs significantly suppressed the breast cancer‐killing ability of T cells compared to vehicle control and con‐EVs, implying that the EV cargo altered by TGF‐β and RAB27B depletion gave EVs a more immunosuppressive effect." (PMID 39723610, 2024). "In our study, we found that TGF‐β signalling inhibits the mRNA and protein expression of RAB27A and RAB27B in a SMAD3‐dependent manner, leading to reduced EV release in breast cancer cells." (PMID 39723610, 2024). "The recomposed EVs, induced by TGF‐β or RAB27B depletion, inhibit CD8+ T cell‐mediated breast cancer killing." (PMID 39723610, 2024). "In the ER + breast cancer, Rab27b activates MMP2 secretion and stimulates breast cancer cell invasion." (PMID 34141705, 2021). "Particularly, we found increased levels of Rab27B, Rab5 and Rab11 in terms of protein expression and mRNA content in AIR breast cancer cells." (PMID 32823947, 2020). "Conversely, ectopic overexpression of Rab27B enhances the proliferation of MCF-7, T47D, and ZR75.1 breast cancer cells in the presence of low serum concentrations." (PMID 30081925, 2018). "Overexpression of Rab27B promotes in vivo tumor growth and the development of hemorrhagic ascites in the peritoneal cavity of animals with MCF-7 breast cancer cell-derived xenografts." (PMID 30081925, 2018). "Ectopic overexpression of Rab27B induces doxorubicin resistance in breast cancer cells and MCF-7 cells stably expressing Rab27B are significantly more resistant to doxorubicin (IC50 = 1.56 μM), compared with that in control MCF-7 cells (IC50 = 0.47 μM)." (PMID 30081925, 2018). "Expression of the V-ATPase V1E1 subunit is markedly increased in breast cancer tissues that also express Rab27B, a member of the RAS oncogene family, suggesting a contribution of V-ATPase V1E1 to breast cancer." (PMID 27384996, 2016).
breast carcinoma (continued). "Recently, we demonstrated that Rab27B regulates invasive tumor growth and metastasis of ER-positive MCF-7, T47D and ZR75.1 breast cancer cells using complementary cell culture and xenograft mouse models." (PMID 21304180, 2010). "Our previous findings indicate that in clinical breast cancer samples, up-regulation of endogenous Rab27B, but not Rab27A, protein correlates with lymph node metastasis and differentiation grade in ER-positive breast tumors." (PMID 21304180, 2010). "Moreover, only Rab27a, not Rab27b, is required for exosome secretion by murine mammary carcinoma cells." (PMID 35053535, 2022). "The differences in localization and expression of both Rab27 proteins in ER-positive and negative breast cancer cell lines could indicate that Rab27A and Rab27B play different roles depending on the cells’ ER-status." (PMID 21304180, 2010). "In our study, in PTX-resistant breast cancer cells, AURKB weakened the negative transcriptional regulation of RAB27B by self-phosphorylation, while phosphorylation of AURKB further enhanced the stability of RAB27B." (PMID 35088239, 2022).
hepatocellular carcinoma (16 papers, 2012 to 2025). A malignant tumor that arises from hepatocytes. "The loss of RAB27B in the HCC cell line (hepatocellular carcinoma) inhibited the PI3K/AKT signaling pathway, leading to suppression of cell proliferation." (PMID 39596498, 2024). "High tumor expression of Rab27A or Rab27B is associated with poor survival of patients with hepatocellular carcinoma." (PMID 32422889, 2020). "In a study of hepatocellular carcinoma, high tumor expression of either Rab27A or Rab27B was shown to be associated with low patient survival rates, whereas high tumor expression of both Rab27A and Rab27B was associated with poor survival." (PMID 30081925, 2018). "Of note, other genes related to exosome release have also been previously related to cancer; for example, high Rab27B levels have been linked to poor prognosis in bladder, pancreatic and colorectal cancer and hepatocellular carcinoma." (PMID 27285987, 2016). "It has been demonstrated that high expression of RAB27B is correlated with poor prognosis in hepatocellular carcinoma, colorectal cancer and ovarian cancer, consistent with our results." (PMID 32379831, 2020). "High expression of Rab27A or Rab27B is significantly correlated with advanced TNM classification in hepatocellular carcinoma." (PMID 30081925, 2018). "Rab27B can also be recognized as a valuable prognostic indicator for hepatocellular carcinoma patients." (PMID 28265202, 2017). "The previous study showed that Rab27B is upregulated in BC; however, Dong et.al reported that the Rab27B expression level was lower in primary hepatocellular carcinoma than in matched adjacent tissues." (PMID 23217148, 2012). "Among those, neutral sphingomyelinase 2 (nSMase2), phosphorylated synaptosome-associated protein 23 (SNAP23) and Ras-related RAB proteins (RAB27A/RAB27B) regulate sEV secretion from different cancer cells like breast cancer, hepatocellular carcinoma (HCC), and colorectal cancer." (PMID 32225076, 2020). "Furthermore, patients with Rab27A (+) or Rab27B (+) exhibit significantly decreased OS compared with those showing Rab27A (−) or Rab27B (−) in hepatocellular carcinoma." (PMID 32432324, 2020). "Moreover, the hepatocellular carcinoma patients with high level of Rab27A or Rab27B significantly reduce the overall survival." (PMID 25823663, 2015). "Previous study revealed that elevated expression of RAB27B in tissues is correlated with hepatocellular carcinoma (HCC) progression; however, the mechanisms involved in promoting HCC development are still unclear." (PMID 28977851, 2017). "RAB27B regulates exosome secretion in a variety of tumors, including PAAD, hepatocellular carcinoma, and colorectal cancer (CRC), and its high expression correlates with tumor cell proliferation and invasion and poor prognosis." (PMID 40141028, 2025). "Notably, Rab27b inhibits exosomal sorting of PD-L1 in hepatocellular carcinoma by diverting PD-L1 from endosomes in the TGN area to the plasma membrane and this effect of Rab27b can be suppressed by GOLM1." (PMID 36320056, 2022).